NODAL (nodal growth differentiation factor)
Diseases named in the same sentence as NODAL in open-access papers (continued):
Sharing a sentence is not in itself a finding about the gene and the disease.
primary ciliary dyskinesia (1 paper, 2022). A rare, genetically heterogeneous, primarily respiratory disorder characterized by chronic upper and lower respiratory tract disease. "However, HTX is genetically heterogeneous, and previous studies have identified multiple genetic mutations involved in establishing left–right asymmetry, including NODAL signaling or primary ciliary dyskinesia-associated disease-causing genes." (PMID 36123719, 2022).
testicular cancer (1 paper, 2015). A primary or metastatic malignant neoplasm that affects the testis. "GDF3 potentiates NODAL activity, but has also been related to the development of testicular cancer formation." (PMID 26630562, 2015).
transposition of the great arteries (1 paper, 2017). A congenital cardiac defect in which two heart vessels are reversed (transposed). "For example, the heterozygous variant p.G260R in NODAL was associated with transposition of the great arteries (TGA), atrial and ventricular septal defects, double outlet right ventricle (DORV) and/or heterotaxy." (PMID 28738792, 2017).
triple-negative breast carcinoma (1 paper, 2020). An invasive breast carcinoma which is negative for expression of estrogen receptor (ER), progesterone receptor (PR), and human epidermal growth factor receptor 2 (HER2). "Finally, SB431542 treatment abrogated hypoxia-induced sphere formation in T47D and SUM149 cells, corroborating that NODAL facilitates plasticity in response to hypoxia in luminal and triple-negative breast cancer cell lines." (PMID 32427827, 2020).
ventricular septal defect (1 paper, 2020). The presence of a defect (opening) in the septum that separates the two ventricles of the heart. "Down-regulation of EBAF in VSD patient tissue is associated with abnormal activation of the NODAL pathway and its target gene pituitary homeobox 2c (PITX2c), which causes ventricular septal defects in humans." (PMID 32765954, 2020). "Therefore, modulation of p300-EBAF axis to normalize NODAL pathway in VSD patients may improve ventricular septal defects." (PMID 32765954, 2020).
cancer (16 papers, 2015 to 2024). A tumor composed of atypical neoplastic, often pleomorphic cells that invade other tissues. "Cancer cells with high levels of NODAL displayed a more aggressive phenotype in vitro, while in vivo was associated with a poorer prognosis in several human cancers, highlighting it as a potential target and marker for targeted cancer therapy." (PMID 36172369, 2022). "Like DIRAS3, NODAL has been recognized for its role in cancer progression, with abundant expression of NODAL associated with cellular migration, invasion, and metastatic behavior." (PMID 26568774, 2015). "Members of the homeobox family as well as NODAL are specifically associated with cancer progression and metastatic behavior." (PMID 26568774, 2015). "In addition, NODAL was found to activate fibroblasts associated with cancer cells and further alter the tumor microenvironment." (PMID 36768435, 2023). "Nodal Growth Differentiation Factor (NODAL) is a TGF-b–related embryonic morphogen expressed in various human cancers, acting as a master regulator of tumor cell plasticity and tumorigenicity." (PMID 38893126, 2024). "NODAL is a fetal development protein that is reactivated in multiple cancer types, where it stimulates the angiogenic activity of VEGF." (PMID 36768435, 2023). "These ligands antagonize NODAL-induced signaling and specifically suppress NODAL-promoted proliferation of cancer cells." (PMID 34349940, 2021). "Using this library and protein morphogen NODAL as a target, we discovered bicyclic macrocycles that specifically antagonize NODAL-induced signaling in cancer cells." (PMID 34349940, 2021). "Noteworthy, NODAL is not only known for its role in cancer progression as it has been originally identified as a morphogen and regulator of mesoderm formation and organization of axial structures during early-stage embryogenesis." (PMID 26568774, 2015). "Aberrant DNA methylation or expression of several HOX genes, NODAL and DIRAS3 have been implicated in the etiology of cancer." (PMID 26568774, 2015). "We then went on to investigate whether expression of NODAL in cancer cells could confer resistance, which constitutes a more physiologically relevant scenario, particularly since NODAL becomes upregulated under hypoxic conditions often found in tumors." (PMID 32636849, 2020). "NODAL is an embryonic protein involved in TGF-β signaling and is highly expressed in various cancers." (PMID 36172369, 2022). "This interactive network was associated with metabolic diseases, peptide hormone metabolism, NODAL signaling, regulation of beta-cell development, WNT ligand biogenesis and trafficking, antimicrobial peptides, PI3K/AKT signaling in cancer, and signaling by the insulin receptor." (PMID 37340445, 2023). "inhibited NODAL/ACTIVIN/TGF-β1 pathway, which could increase cancer stem cells(CSC)’ chemoresistance." (PMID 29254283, 2017).
tumor (16 papers, 2015 to 2024). "The TGFβ family member NODAL, repeatedly required during embryonic development, has also been associated with tumour progression." (PMID 37987367, 2023). "Due to its absence in most normal adult tissues and overexpression in aggressive tumor cells, NODAL is considered a potentially valuable therapeutic target." (PMID 38893126, 2024). "This enhanced the engagement of JAGGED on N2-TAN/gMDSC, known to favor tumor cell proliferation, and elevated NODAL production and release by tumor cells." (PMID 38334604, 2024). "The NODAL expression in tumour cells has been correlated with their plasticity and invasive behaviour, in line with its functions in embryonic and adult tissues." (PMID 37987367, 2023). "The effects of the L1CAM, CXCR4 and NODAL on tumor growth, proliferation, migration, invasion, colony-formation ability, metastasis and chemoresistance were investigated both in vitro and in vivo." (PMID 33897875, 2021). "To better understand the effect of Nodal on tumor cell behavior, we forced the system by treating the PDOs with NODAL recombinant protein (rNODAL)." (PMID 33897875, 2021). "While short NODAL treatment increased the tumor initiation frequency (TIC) in PDO#2 and PDO#5 of 2 and 2.3 times, respectively, it does not alter TIC in the PDO#1, as expected." (PMID 33897875, 2021). "NODAL is an embryonic morphogen secreted by tumor cells in the TME, whose aberrant expression is induced under hypoxia." (PMID 32636849, 2020). "We also recognize that the presence of γδ T cells near NODAL-expressing tumor cells suggests that, if there is an inhibitory effect of NODAL on γδ T cell migration to the tumor, γδ T cells are able to overcome this, at least partially." (PMID 32636849, 2020). "Human NODAL has been implicated in the maintenance of ESC cell pluripotency and in tumor metastasis." (PMID 29059375, 2018). "JAM-A indicated the sensitivity of B-lymphoma cells to lenalidomide, and therapeutic targeting of JAM-A/NODAL axis represents a promising clinical strategy to counteract tumor progression in DLBCL." (PMID 28785100, 2017). "We also found that GAS5 increased NODAL expression, while reducing the expression of its targeting miRNAs in these tumours." (PMID 27811843, 2016). "In addition, NODAL has been shown to modulate tumor cell plasticity by promoting the formation of angiogenic mimetic structures." (PMID 38874512, 2024). "In addition, we also observed a higher expression of NODAL in tumor tissue compared to normal colonic epithelium." (PMID 33897875, 2021). "NODAL promotes tumor growth in Nude mice bearing a partial immune system, but this effect diminishes when more immunodeficient models are used, suggesting a role for NODAL in immune evasion." (PMID 32636849, 2020). "We can confirm, however, that γδ T cells could be found in close proximity to tumor cells, some of which expressed NODAL, but that most γδ T cells were localized in the adjacent tumor stroma." (PMID 32636849, 2020). "Thus, NODAL perhaps mediates tumor cell escape by somehow regulating expression of surface MICA, the exact mechanism of which remains to be determined." (PMID 32636849, 2020). "In all cases in which γδ T cells could be identified in these tumors, γδ T cells were found in close proximity to NODAL-expressing tumor cells." (PMID 32636849, 2020). "In all cases in which both NODAL and γδ T cells could be detected, γδ T cells were found in close proximity to NODAL-expressing tumor cells; proximity was defined by a distance of < 50 μm." (PMID 32636849, 2020). "There is a significant inverse correlation of NODAL with MICA/B on the tumor cell surface." (PMID 32636849, 2020). "Therapeutic targeting of JAM-A/NODAL axis could thus be a promising clinical strategy to impede tumor progression in DLBCL." (PMID 28785100, 2017). "According to the RNA-seq analysis, NRP2, NODAL, and NR2F2 were highly expressed, while EGF was lowly expressed in tumour tissue." (PMID 36172369, 2022).
tumor (continued). "We analyzed by qPCR the level of NODAL in Human Normal Mucosa samples (n = 3) versus Human primary CRC (n = 10) and we observed a significant increase of NODAL expression in tumor samples as compared to healthy tissue samples." (PMID 33897875, 2021). "One patient (St23784/17) had amplifications in the 3q, 6q, 8q, 9q, and 10q22.1 regions of stemness gene localization in her tumor (the following genes were amplified: SOX2, MYC, KLF4, NOTCH1, NODAL)." (PMID 32523653, 2020). "We would like to thank Dr. Raymond Lai for helping us to obtain tumor sections from the TNBC cohort, Guihua Zhang for NODAL IHC staining and Dylan Dieters-Castator for advice and assistance with preparation of conditioned medium from MDA-MB-231 shN and shC cell lines." (PMID 32636849, 2020). "Since NODAL is a secreted protein, which would not be captured by IHC, it is reasonable to infer that the NODAL produced by tumor cells would come into contact with γδ T cells in the TME." (PMID 32636849, 2020). "In a murine xenograft model established with subcutaneous injection of JAM-A-overexpressing B-lymphoma cells, lenalidomide retarded tumor growth and prevented cell invasion to mesoendoderm-derived organs, consistent with the downregulation of JAM-A and NODAL expression." (PMID 28785100, 2017). "Furthermore, tumor derived from PDOx_SC exhibited co-expression of L1CAM and NODAL or pSMAD2, suggesting again that L1CAM expression may be functionally linked to NODAL signaling." (PMID 33897875, 2021). "Thus in our case, signals form the tumor stroma inhibit BMP, which leads to derepression of NODAL." (PMID 26226633, 2015). "Our results argue that the NODAL protein plays no role, but that a natural antisense transcript, which we have named LADON, and which overlaps with the NODAL exon 2, promotes tumour progression and invasion." (PMID 37987367, 2023).
infection (2 papers, 2021). The state of being infected such as from the introduction of a foreign agent such as serum, vaccine, antigenic substance or organism. "Our previous research showed that infection of bronchial epithelial cells (BECs) by different microorganisms will show effects on the expression of NODAL." (PMID 34541002, 2021). "The organoid infection induced the downregulation of NODAL, an important growth factor for pluripotency stem cell maintenance, impairing appropriate neural development." (PMID 34696533, 2021). "In order to detect the expression of NODAL signaling pathway, we infected BECs with RSV for 48 h and confirmed the infection using IFA." (PMID 34541002, 2021).
NODAL also shares sentences with these, for which no sentence is quoted: gastric cancer (2 papers); asthma (1); ciliopathies (1); DiGeorge syndrome (1); fetal growth restriction (1); Hypertension (1); idiopathic pulmonary fibrosis (1); liver cancer (1); metabolic disease (1); metastatic tumor (1); ovarian carcinoma (1); pneumonia (1); situs inversus (1); testicular tumors (1); type 2 diabetes (1); Wilms tumour (1).